PIK3CA (phosphatidylinositol-4,5-bisphosphate 3-kinase catalytic subunit alpha)
Diseases named in the same sentence as PIK3CA in open-access papers (continued):
Sharing a sentence is not in itself a finding about the gene and the disease.
breast cancer (continued). "Thus, we also assessed whether INPP4B overexpression confers sensitivity of PIK3CA-mutant ER+ breast cancer cells to alpelisib." (PMID 36612130, 2022). "In patients with HER2-positive breast cancer we found no impact of PIK3CA-mutations on RFI." (PMID 36279023, 2022). "Therefore, we speculate that high expression of LSM1 may be associated with mutations in the PIK3CA gene leading to uncontrolled cell division and recovery, which in turn affects the significant elevation of LSM1 in breast cancer." (PMID 35692083, 2022). "Interestingly PIK3CA-mutant breast cancers also display low dependence on AKT signaling for unknown reasons." (PMID 34035258, 2021). "Activation mutations in PIK3CA, the gene encoding the catalytic subunit of PI3K, p110a, occur in 48% of invasive lobular carcinoma and in 41%, 40%, 31%, and 14% of hormone-positive HER2-negative (HR+HER2), HR+HER2+, HR-HER2+, and triple-negative breast cancer (TNBC) breast cancer, respectively." (PMID 35578699, 2021). "PIK3CA, which has started to be highlighted in recent years, has undeniable worth in understanding molecular pathogenesis for canine tumors, and could be a potential therapeutic target in canine mammary tumors." (PMID 34359206, 2021). "In this study, we conducted a large‐scale prospective study using the Fudan breast cancer‐specific NGS panel, summarising the correlation between clinical and genomic variation in RTK‐PI3K‐MAPK pathways, and illustrated the adaptive roles of PIK3CA mutations in HER2+ tumour progression." (PMID 34842356, 2021). "Pooled mutation‐barcoding library, containing 119 PIK3CA mutations and controls, were conducted to achieve precise annotation of impactful PIK3CA mutations that determine the proliferation ability of HER2+ mammary cancer cells and drug responses under different treatments." (PMID 34842356, 2021). "Previously, decreased H3K4me3 by AKT inhibitor MK2206 in PIK3CA-mutated TNBC cells was shown to be associated with the suppressed expression of aurora kinase B (AURKB), proliferating cell nuclear antigen (PCNA) and other genes that are critical to breast cancer survival." (PMID 33664847, 2021). "Therefore, tumours carrying PIK3CA mutations grew slower than wild‐type tumours both in vivo and in vitro, which might be a unique phenotype for HER2+ breast cancer." (PMID 34842356, 2021). "For instance, TNBC patients bearing mutations in PIK3CA, AKT1, and ESR1, as well as EGFR amplifications, may be treated with different drugs to those that are used to treat other subtypes of breast cancer (BRCA) and Non-Small Cell Lung Cancer (NSCLS), respectively." (PMID 34680239, 2021). "For example, MEX3A may act as a tumor promoter for breast cancer by regulating PIK3CA." (PMID 34189143, 2021). "However, the cell lineage may affect the pharmacologic sensitivity to Akt1/2 inhibition, for instance, PIK3CA-mutant breast cancer cell lines are more sensitive than PIK3CA-mutant colon cancer cell lines." (PMID 33916378, 2021). "Moreover, we show there is potentially clinical importance in understanding both the PIK3CA mutational status and levels of neuregulin-1 expression in patients with HER2-amplified breast cancer treated with targeted therapy and that these problems warrant further pre-clinical and clinical testing." (PMID 34344439, 2021).
breast cancer (continued). "Interestingly, taselisib as monotherapy has limited therapeutic activity in PIK3CA breast cancer." (PMID 34769309, 2021). "Alpelisib (PIQRAY, Novartis Pharmaceuticals Corporation), a PI3K inhibitor, received FDA approval in combination with fulvestrant for patients with hormone receptor (HR)-positive, human epidermal growth factor receptor 2 (HER2)-negative PIK3CA-mutated advanced breast cancer." (PMID 32983983, 2020). "In May 2019, alpelisib, a novel first-in-class oral small molecule PIK3CA-isoform–specific inhibitor, received Food and Drug Administration (FDA) approval for the treatment of metastatic ER+ breast cancer harboring PIK3CA mutations following progression of disease on or after treatment with ET." (PMID 33144920, 2020). "No studies have evaluated whether the effect of PIK3CA mutation status on breast cancer outcomes differs by aspirin use." (PMID 32326897, 2020). "As reported, PIK3CA mutations occurred in 20–50% of breast cancers, especially including 35% of hormone receptor (HR)-positive breast cancers, 23% of human epidermal growth factor receptor 2 (HER2)-positive breast cancers and less than 10% in triple-negative breast cancer (TNBC)." (PMID 30754640, 2019). "Additionally, we identified the alterations of epigenetic targets, such as SWI/SNF related genes (SMARCA2, SMARCA4, SMARCA5) or histone modifiers (KMT2C or KMT2D), breast cancer-associated oncogenes (MYCN or MAPKs), or genes that are involved in drug-resistance (ESR1 and PIK3CA/B)." (PMID 31216647, 2019). "Carcinogen-induced mammary tumors in rats are ovarian-hormone dependent (70% ER+; 30% ER-), but these carcinogens are not implicated in human breast cancer although several of the mutations initiated by them, such as those in PIK3CA, are also commonly observed in human breast tumors." (PMID 30893315, 2019). "To investigate single cell mutational analysis, we tested whether a known PIK3CA mutation in the PDX model BCM-4888 [T1035A (N345K)] could be identified in individual CTCs, using disaggregated cells from the primary mammary tumor or lung metastasis as controls." (PMID 30871481, 2019). "Interestingly, several recent reports have shown that INPP4B overexpression could be detected in other cancer contexts, such as PIK3CA-mutant breast cancer and a subset of melanoma." (PMID 29343273, 2018). "The applied human epithelial MCF10 breast cancer progression model compares the near‐diploid non‐malignant cell line MCF10A forming polarized spheroids with the tumorigenic invasively growing line MCF10CA, which bear activating mutations of HRAS and PIK3CA, and amplified MYC." (PMID 30104419, 2018). "This may indicate that though the PIK3CA gene mutation is important to the occurrence of breast cancer it is not influential to the survival time of patients." (PMID 30045691, 2018). "The majority of genotype-matched clinical trials available at our institution during the study period involved a PI3K inhibitor and most trials did not involve alpha isoform-selective/specific PI3K inhibitor that may have greater activity in PIK3CA mutant breast cancers." (PMID 29177603, 2018). "This study aimed to investigate whether PIK3CA mutations identified in archived formalin‐fixed, paraffin‐embedded (FFPE), metastatic tissue samples of breast cancer patients could also be detected in their corresponding ctDNA from serum samples using an optimized droplet digital PCR (ddPCR) assay." (PMID 29689598, 2018).
breast cancer (continued). "Also, out of a total of 95 breast cancer samples, there were 5 breast-cancer samples which did not have mTOR-pathway activation, and all 5 (100%) of these had PIK3CA and PTEN mutations compared to 51/90 (57%) in the breast-cancer samples with mTOR-pathway activation (χ2p=0.0134)." (PMID 29137436, 2017). "The breast cancer network model we present in this work integrates the current knowledge of PIK3CA-mutant, ER+ breast cancers, and uses it to identify a set of elements that may eventually be exploited in high-order therapeutic combinations to achieve a more durable control of breast cancer." (PMID 29623959, 2017). "Of the cancer types with 10 or more representative samples, PIK3CA and/or PTEN mutations were most prevalent in hepatocellular carcinoma samples (11/16; 69%), triple-negative breast-cancer samples (18/27, 67%), endometrial-carcinoma samples (10/17, 59%), and HR+ breast-cancer samples (31/61; 51%)." (PMID 29137436, 2017). "To test whether the PIK3CA mutations correlate with survival in luminal A breast cancer patients, we conducted a survival analysis comparing PIK3CA-mutated and PIK3CA non-mutated patient tumor samples." (PMID 28392480, 2017). "PIK3CA mutation, HER2 amplification as well as PTEN mutation are frequently found in breast cancer, suggesting that PI3K might be a promising target for breast cancer therapy." (PMID 26918351, 2016). "For example, a low grade breast cancer contains only a PIK3CA mutation without other driver abnormalities may be a good candidate for PIK3CA inhibitor therapy." (PMID 27283966, 2016). "The same may not be true for IGF signaling: it is known that PIK3CA-mutated breast cancer cells remain responsive to IGF stimulation and are growth delayed by IGF-1R inhibition." (PMID 27200287, 2016). "In samples from patients with advanced metastatic breast cancer (cohorts B and C), we obtained 98.0 % and 97.1 % concordance and an AKT1E17K mutation capture rate of 66.7 % and 85.7 % for ctDNA, and 100 % concordance and a PIK3CA mutation capture rate of 100 % (cohort B)." (PMID 27515171, 2016). "Our results divulged that breast cancer, leukemia and colorectal carcinomas were the most sensitive cancer cell types to ARQ 092 and that cell lines bearing PIK3CA/PIK3R1 mutations were more responsive to ARQ 092 (53%) compared to cells containing WT-PIK3CA/PIK3R1 (24%)." (PMID 26469692, 2015). "Other studies found that PIK3CA mutations are more frequent in HER2+ and luminal breast cancer; it might be that we defined a subgroup of TNBCs where PIK3CA mutations are also frequent, i.e., the non-BRCA subgroups." (PMID 26433948, 2015). "The potential association between PIK3CA mutational status and T-DM1 efficacy remains unknown, but the results from clinical breast cancer series suggest that trastuzumab benefit does not depend on the mutational status of PIK3CA or tumor PTEN expression." (PMID 24887180, 2014).
breast cancer (continued). "Nevertheless, in three smaller clinical studies in patients with HER2-positive breast cancer, PIK3CA mutations and PTEN loss did not impact the efficacy of lapatinib, whether administered alone or in combination with chemotherapy." (PMID 25056500, 2014). "This might explain why we observed a higher frequency of PIK3CA exon 9 mutations in nonlobular breast cancer compared with the studies from Buttita and Barbareschi." (PMID 24467828, 2014). "Paradoxically, PIK3CAmutations are associated with a gene signature of low mTORC1 signaling and betteroutcomes in ERα + breast cancer.It will be interesting to see whether the genetically defined ERα + PIK3CA-mutant model we have developed can shed freshlight on this problem." (PMID 25527189, 2014). "Recently, it has been shown that PDK1 regulates anchorage-independent growth, resistance to several anticancer drugs, and tumor formation in breast cancer cells–not only in tumors harboring PIK3CA mutations, but also in the absence of these genetic alterations." (PMID 24739482, 2014). "In patients randomized to the control arm, we did not observe an association between PIK3CA mutations, or any of the other tested molecular aberrations, and breast cancer prognosis, when corrected for known prognostic factors, such as the PgR status and histologic tumor grade." (PMID 24467828, 2014). "Considering our observations in ERα-positive early breast cancer patients, it is not likely that PIK3CA hotspot mutation status by itself would be a suitable companion diagnostic predicting benefit from the putative use of PI3K/AKT/mTOR inhibitors in the adjuvant setting." (PMID 24467828, 2014). "Somatic PIK3CA mutation is present in familial male breast cancer but absent in BRCA2 carriers." (PMID 23971979, 2013). "At this moment, it remains unclear whether activation of the PI-3 K/Akt signaling by any means, such as PIK3CA mutation or phosphatase and tensin homolog (PTEN) deletion in addition to erbB2/erbB3 receptors, would also enhance expression of Survivin in breast cancer cells." (PMID 24168763, 2013). "Notably, only 6.5% of OSCC patients harbored at least one PIK3CA and HRAS mutation, whereas, these oncogenic mutations occur in 30-70% of solid tumours, including colorectal, ovarian, endometrial, lung, melanoma and breast cancer." (PMID 24224046, 2013). "Furthermore, we examine whether expression of PIK3CA and PTEN mRNA and occurrence of PIK3CA mutations are associated with lymph node metastases in patients with primary breast cancer." (PMID 24083111, 2013). "Interestingly, there is a clear correlation between increased pAkt and loss of PTEN (but not with mutations in PIK3CA) in human tumors and breast cancer cell lines." (PMID 23448424, 2013). "Thus, as the incidence of PIK3CA mutations in tumours from in BRCA2 carriers is likely to be negligible, these patients are unlikely to derive benefits from the PIK3CA inhibitors that are now entering clinical trials for female breast cancer." (PMID 23971979, 2013). "For example, PDK1, but not AKT, is activated in some breast cancers with PIK3CA mutations." (PMID 22666248, 2012). "For example, in ovarian cancer cells both PIK3CA mutations and PTEN deficiency have been reported to predict PI3K pathway inhibitor response, whereas in breast cancer the associations between PTEN loss of function and response are less clear, which will be discussed in greater detail below." (PMID 22970424, 2012). "However, it remains possible that PIK3CA promoter SNPs that were not captured in this study are related to breast cancer risk." (PMID 22033276, 2011). "This suggests that PIK3CA might be a promising therapeutic target in breast cancer." (PMID 16168105, 2005). "The results of the analysis of the CTC number and ESR1 and PIK3CA mutations in blood collected from 179 patients with metastatic breast cancer show that ESR1 mutations are more frequent in patients with advanced luminal breast cancer regardless of the type of the treatment." (PMID 40076662, 2025).
breast cancer (continued). "The authors used BYL719 or AZD8186 compounds described as selective inhibitors of PI3Kα or PI3Kβ, respectively, in mutant PIK3CA MCF-7 and mutant PTEN HCC70 breast cancer cells." (PMID 39746759, 2025). "In patients with PIK3CA-mutant, HR+/HER2– advanced breast cancer, the addition of inavolisib to palbociclib and fulvestrant substantially extended PFS to 17.2 months compared to 7.3 months with placebo." (PMID 40989687, 2025). "Alteration of this pathway occurs via mutations in oncogenes, such as the catalytic subunit of the class I PI3K (PIK3CA) or AKT1, in ~40% and ~7% of estrogen receptor positive (ER+) breast cancers, respectively." (PMID 41408399, 2025). "Expert Group Recommendations: It is advised to assess alterations in the PIK3CA, AKT1, and PTEN genes in patients with HR‐positive advanced breast cancer who experience disease progression following endocrine therapy." (PMID 40206206, 2025). "Furthermore, research indicates that the presence of mutant PIK3CA circulating tumor DNA (ctDNA) before surgery is associated with poorer outcomes, including shorter relapse-free survival and overall survival, regardless of the specific breast cancer subtype." (PMID 40050490, 2025). "Other interesting observations included the mutual exclusivity of KEAP1 and STK11 in NSCLC and enrichment for CDH1, PIK3CA, and ARID1A along with mutual exclusivity with BRCA1/2, PTEN, and ESR1 in breast cancer." (PMID 40178042, 2025). "Lastly, Capivasertib (AZD5363), an oral AKT inhibitor, has shown promise in phase I trials for PIK3CA‐mutant breast cancer and other solid tumors, with ongoing phase II trials like FAKTION (Capivasertib) in breast cancer." (PMID 41163374, 2025). "Further research and prospective validation in dedicated studies are essential to comprehensively assess the impact of PIK3CA status and different CDK4/6 inhibitors on clinical outcomes in HR+/HER2- advanced breast cancer." (PMID 40740245, 2025). "Additionally, it was covered by insurance in Japan in May 2024, and the detection of PIK3CA, AKT1, and PTEN alterations by FoundationOne CDx is a companion diagnosis for the use of capivasertib in HR-positive HER2-negative advanced breast cancer with PIK3CA, AKT1, or PTEN alterations." (PMID 39466567, 2025). "Among HER2 + stage I-III breast cancers with early (N = 20) and late (N = 20) recurrence, the most frequent alteration, other than HER2 amplification, was PIK3CA (45% vs 25%), followed by BRCA1/2 (10% vs 5%), ESR1 (0% vs 5%), PD-L1 amplification (5% vs 0%)." (PMID 40421962, 2025). "Thymol derivatives, such as 1,2,3‐triazoles and carvacrol, effectively target breast cancer (BC) through PI3K/AKT/mTOR and NOTCH pathways and inhibit PIK3CA expression." (PMID 40964147, 2025). "This study demonstrated that GluOC facilitates the migration of MDA-MB-231 breast cancer cells through the ROCK1/MYPT1/MLC2 signalling pathway and promotes the proliferation of TNBC cells via the ROCK1/JAK2/PIK3CA/AKT signalling pathway." (PMID 39054484, 2024). "To date, only four GEMMs have been reported to develop HR+ mammary tumors: the Stat1-knockout, BLG-Cre; Kras(G12V), NRL-PRL, and Wap-Cre; Pik3ca(H1047R) models." (PMID 38913216, 2024). "The international data sharing consortium, AACR Project GENIE, showed that genetic alterations in PIK3CA, PTEN and AKT1 occur in ~36%, 7% and 5% of breast cancer, respectively." (PMID 39251829, 2024).